METTL5 (methyltransferase 5, N6-adenosine)
Diseases named in the same sentence as METTL5 in open-access papers (continued):
Sharing a sentence is not in itself a finding about the gene and the disease.
pancreatic cancer (3 papers, 2023 to 2024). "Moreover, METTL5 is identified as an oncogene in pancreatic cancer, promoting cell proliferation, migration, invasion, and tumourigenesis." (PMID 38797935, 2024). "Additionally, METTL5 works with TRMT112 to enhance pancreatic cancer progression, positioning the METTL5/c Myc axis as a potential therapeutic target." (PMID 38797935, 2024). "Interestingly, METTL5 (a methyltransferase that specifically catalyzes 18 S rRNA N6 methylation at adenosine 1832) was considered an oncogene that promoted pancreatic cancer progression synergistically with its cofactor TRMT112 (tRNA methyltransferase activator subunit 11‐2)." (PMID 36977668, 2023).
uterine corpus endometrial carcinoma (2 papers, 2022 to 2024). A endometrial carcinoma (disease) that involves the body of uterus. "METTL5 expression is elevated in uterine corpus endometrial carcinoma, and uterine corpus endometrial carcinoma patients with high METTL5 expression have a poorer prognosis." (PMID 39289775, 2024).
airway allergy (1 paper, 2025). "In airway allergy (AA) mouse models, METTL5 expression was significantly upregulated in M2 macrophages and positively correlated with Th2 polarization." (PMID 41487998, 2025). "Thus, Mettl5 acts as a positive regulator of airway allergy by weakening M2 immunosuppression and promoting Th2 responses, suggesting that its inhibition may represent a therapeutic strategy for allergic diseases." (PMID 41487998, 2025).
autosomal recessive intellectual developmental disorder-72 (1 paper, 2025). "Pathogenic biallelic variants in METTL5 have been associated with autosomal recessive intellectual developmental disorder-72 (MRT72; OMIM #618665)." (PMID 41465175, 2025).
autosomal recessive intellectual disability (1 paper, 2025). "NSUN2 is known to cause forms of autosomal recessive intellectual disability (AR ID) as are methyltransferases from other modification systems, e.g. FTSJ1, a human tRNA 2′-O-methyltransferase, and METTL5, an N6 adenine DNA and rRNA writer." (PMID 39499421, 2025).
cholangiocarcinoma (1 paper, 2025). A carcinoma that arises from the intrahepatic biliary tree (intrahepatic cholangiocarcinoma) or from the junction, or adjacent to the junction, of the right and left hepatic ducts (hilar cholangiocarcinoma). "Recent studies have reported the critical role of METTL5 in promoting the progression of various cancers, including gastric, liver, cholangiocarcinoma, and colorectal cancer." (PMID 40750759, 2025).
cognitive deficits (1 paper, 2026). "Methyltransferase-like 5 (METTL5) is a methyltransferase responsible for rRNA N6-methyladenosine (m6A) modification, mutations in which are associated with skeletal abnormalities and cognitive deficits." (PMID 42100868, 2026).
glioblastoma (1 paper, 2025). The most malignant astrocytic tumor (WHO grade IV). "Eleven out of sixteen published ICB cohorts showed downregulated METTL5 expression in patients with clinical benefit, with statistically significant downregulation observed in one cohort of glioblastoma patients." (PMID 41042068, 2025).
heart failure (1 paper, 2022). Inability of the heart to pump blood at an adequate rate to meet tissue metabolic requirements. "In contrast, loss of METTL5 promoted TAC-induced cardiac remodeling with progression to heart failure in the METTL5-cKO group, which was associated with significantly increased left ventricular internal dimension (LVID) and dramatic reduced fraction shortening (FS)." (PMID 35295259, 2022). "In addition, the expression level of METTL5 in human samples collected from patients with heart failure was also tested." (PMID 35295259, 2022).
Huntington disease (1 paper, 2023). Huntington disease (HD) is a rare neurodegenerative disorder of the central nervous system characterized by unwanted choreatic movements, behavioral and psychiatric disturbances and dementia. "Acting on a Heme group of donors with Heme-copper terminal oxidase activity, METTL5 were proven to largely participate in the signaling pathways of ribosome, oxidative phosphorylation, spliceosome, Parkinson disease, proteasome, and Huntington disease." (PMID 37400463, 2023).
Infertility (1 paper, 2025). "Increasing evidence suggests that loss or mutation of METTL5 is closely associated with developmental abnormalities, neurological disorders, and infertility, highlighting its indispensable role in maintaining physiological homeostasis and counteracting pathological challenges." (PMID 41487998, 2025). "In a cohort of 1,427 infertile men with oligoasthenoteratozoospermia (OAT), four pathogenic heterozygous variants of METTL5 were identified, all associated with significantly reduced METTL5 expression." (PMID 41487998, 2025).
melanoma (1 paper, 2025). A malignant, usually aggressive tumor composed of atypical, neoplastic melanocytes. "Similar regulatory mechanisms of ATF4 by METTL5 were also reported in melanoma cell lines." (PMID 41042068, 2025).
monoclonal gammopathy of undetermined significance (1 paper, 2025). "To further understand the importance of METTL5 during the progression of MM, we also assessed METTL5 expression in patients with monoclonal gammopathy of undetermined significance (MGUS) and smoldering MM (SMM), which are considered precancerous conditions of MM." (PMID 40750759, 2025).
multiple myeloma (1 paper, 2025). "Existing research has confirmed that inhibiting protein translation is highly effective against myeloma, which aligns with our findings that suppressing METTL5 and its mediated protein translation effectively curbs MM progression." (PMID 40750759, 2025). "However, the functionality and molecular mechanisms of METTL5 in the progression of multiple myeloma (MM) remain unknown." (PMID 40750759, 2025).
oral squamous cell carcinoma (1 paper, 2026). "Our previous studies have established that METTL5 is significantly overexpressed in oral squamous cell carcinoma (OSCC), correlating with advanced tumor stage, reduced survival rates, and alterations in immune response." (PMID 41551838, 2026).
ovarian carcinoma (1 paper, 2025). A malignant neoplasm originating from the surface ovarian epithelium. "Overall, our data indicate that the axis of METTL5‐ATF4‐SLC7A11/SLC3A2 plays a vital role in promoting immune resistance in ovarian cancer models and patients, and targeting METTL5 could improve the effectiveness of immunotherapy in OC patients." (PMID 41042068, 2025). "These insights warrant further studies to evaluate the potential of METTL5 as a prognostic biomarker and therapeutic target for ICB‐based therapies in ovarian cancer patients." (PMID 41042068, 2025).
pancreatic adenocarcinoma (1 paper, 2025). "Furthermore, upregulated METTL5 expressions were observed in OC, large B‐cell Lymphoma (DLBC), thymoma (THYM), liver hepatocellular carcinoma (LIHC), pancreatic adenocarcinoma (PAAD), and kidney renal clear cell carcinoma (KIRC) compared to corresponding normal tissues." (PMID 41042068, 2025).
renal cell carcinoma (1 paper, 2025). "In renal cell carcinoma (RCC), METTL5 was significantly overexpressed in both clear cell RCC (KIRC) and papillary RCC (KIRP), correlating with tumor stage, grade, and poor prognosis." (PMID 41487998, 2025).
cancer (24 papers, 2021 to 2026). A tumor composed of atypical neoplastic, often pleomorphic cells that invade other tissues. "METTL5, a newly discovered regulator, has been associated with cancer biology due to its capability to influence gene expression in an m6A-dependent manner." (PMID 41551838, 2026). "Functionally, the loss of METTL5 leads to translational reprogramming in both cancer cells and mouse models, with Mettl5-deficient mice displaying reduced body size and metabolic defects." (PMID 41487998, 2025). "In the cancer setting, pan-cancer database analyses have linked METTL5 expression to immune regulation." (PMID 41487998, 2025). "Loss of METTL5 influences gene expression at the translational level in human cancer cell lines and mice, with METTL5 knockout mice exhibiting reduced body size and metabolic defects." (PMID 38797935, 2024). "Many cancers overexpress METTL5 compared to the normal tissues, which has been associated with poor outcomes." (PMID 37047306, 2023). "We show that loss of METTL5 in human cancer cell lines and in mice regulates gene expression at the translational level; additionally, Mettl5 knockout mice display reduced body size and evidence of metabolic defects." (PMID 35033535, 2022). "Consequently, abnormal expression of METTL5 may constitute a significant pathogenic mechanism in numerous cancer types and thus deserves further investigation." (PMID 40750759, 2025). "Here, the aim is to identify the role of METTL5, the 18S rRNA m6A methyltransferase, in regulating the liver immune microenvironment to promote cancer progression." (PMID 41431992, 2025). "We then evaluate current evidence linking METTL5 to human diseases, with a particular focus on neurodevelopmental disorders and cancer." (PMID 41487998, 2025). "In contrast, cancer cells frequently exploit METTL5 to sustain oncogenic translation programs, metabolic adaptation, and immune evasion." (PMID 41487998, 2025). "Our data, combined with the analysis of published ICB cohorts, suggests that the correlation between high METTL5 expression and an immune‐resistant phenotype varies across different cancer types." (PMID 41042068, 2025). "In recent years, accumulating evidence has revealed that METTL5, as an 18S rRNA m6A methyltransferase, plays a crucial oncogenic role in the initiation and progression of various cancers." (PMID 41487998, 2025). "The 18S ribosomal RNA (rRNA) m6A methyltransferase Methyltransferase-like 5 (METTL5) is upregulated in various cancers, leading to adverse prognosis by abnormally regulating protein translation in tumor cells." (PMID 40750759, 2025). "From this, we conjectured METTL5, besides its own ability to promote cancer cell proliferation and invasion, also regulates tumor immunity to further accelerate HCC progression." (PMID 38613157, 2024). "METTL5, one of the extensively studied methyltransferases of 18srRNA, increases protein translation in cancer, decreases cell apoptosis, and enhances cell cycle progression." (PMID 38613157, 2024). "The METTL5/TRMT112 complex is crucial in cancer progression, primarily through its role in rRNA modification." (PMID 38797935, 2024). "Considering the fact that METTL5 is mostly found to be upregulated in other cancer types and gas oncogenic functions, it will be interesting to investigate the reason for the downregulation of METTL5 in PCa and uncover its clinical relevance." (PMID 37033963, 2023). "We calculated the differential expression of the METTL5 gene in various types of cancers and matched normal tissues by means of online searching at the GEPIA database." (PMID 37400463, 2023). "A growing body of evidence displayed that the aberrant expression of METTL5 existed in a wide variety of human malignant tumors." (PMID 37400463, 2023). "ACSL4 regulates the role of METTL5 in fatty acid metabolism and thus facilitates cancer progression." (PMID 37055798, 2023).
cancer (continued). "METTL5 has been shown to regulate the differentiation of embryonic stem (ES) cells and the growth of cancer cells." (PMID 35295259, 2022). "Of the 30 METTLs, expressions of eight (METTL1, METTL7B, METTL5, NTMT1, METTL2A, METTL2B, EEF1AKNMT, METTL6) were significantly (FDR < 0.05) associated with unfavorable overall survival across cancers." (PMID 34285249, 2021). "The pathways that were found to be enriched indicate that TRMT112 could be instrumental in the development and progression of cancer, potentially collaborating with the METTL5 oncogene." (PMID 41551838, 2026). "In different tumor types, its role can be even opposite: in some cancers, METTL5 acts as an oncogene by enhancing the translation of pro-tumor transcription factors, whereas in other tumors, its loss impairs cell survival, reflecting a role in maintaining basal translational homeostasis." (PMID 41487998, 2025). "To clarify the carcinogenic and cancer-promoting role of METTL5, we utilized an overexpression lentivirus to elevate the expression of METTL5 in RPMI-8226 and H929 cells, and conducted functional phenotype detection by qPCR and western blot analyses to confirm overexpression." (PMID 40750759, 2025). "Furthermore, these observations raise the possibility that METTL5-mediated translational control represents a common mechanistic node linking tumor growth, metabolism, and proliferation across cancers." (PMID 41487998, 2025). "Studies have found that METTL5 may be related to various biological processes such as cell stress response and cancer, so its function and regulatory mechanism are still one of the hot topics in current biomedical research." (PMID 40018408, 2025). "For instance, in multiple disease models, including cancer, metabolic disorders, and neurological diseases, METTL5 is frequently attributed to similar mechanisms such as modulating translation efficiency, influencing stress responses, and promoting cell proliferation." (PMID 41487998, 2025). "Notably, upregulation of METTL5 is prominent in OC compared to most other cancer types, and high METTL5 expression is significantly associated with immunotherapy resistance in HGSOC." (PMID 41042068, 2025). "Although METTL5 is required for normal development and homeostasis, its mechanism of action in physiological tissues may differ from that in cancer." (PMID 41487998, 2025). "Comprehensive dissection of METTL5 function in immune cells may reveal novel combinatorial targets for cancer immunotherapy." (PMID 41487998, 2025). "Exon skipping in genes such as TUBB6, FGFR1, cAMP-dependent protein kinase inhibitor gamma (PKIG), and METTL5 was observed, which could lead to the development of cancer or affect a normal function of nervous system." (PMID 40395612, 2024). "Moreover, acyl-CoA synthetase long-chain family member (ACSL4) regulates the function of METTL5 in fatty acid metabolism and thus facilitates cancer progression." (PMID 37055798, 2023). "METTL5 expression were enriched in the signaling pathways of ribosome and oxidative phosphorylation, mismatch repair, and spliceosome through the involvement of several cancer-related kinases and miRNAs." (PMID 37400463, 2023). "Moreover, cancer-specific regulatory networks, such as aberrant transcriptional activation or altered metabolic states, may enhance METTL5 dependency." (PMID 41487998, 2025). "Emerging evidence also indicates that aberrant METTL5 expression or activity may contribute to tumorigenesis by influencing cancer cell proliferation, metabolic rewiring, and therapeutic sensitivity, highlighting its potential as both a biological regulator and a disease-associated factor." (PMID 41487998, 2025).
cancer (continued). "In addition to immunomodulation, METTL5 blockade may also sensitize cancer cells to ferroptosis-inducing agents and metabolic stress, suggesting a synergistic strategy when combined with existing therapies." (PMID 41487998, 2025). "Targeting METTL5 inhibition may hold substantial therapeutic potential in cancer progression." (PMID 41487998, 2025). "Our findings highlight how METTL5 regulates gene expression and disease progression during MM, and provide a molecular foundation for the development of therapeutic strategies aimed at targeting this pathway to achieve better therapeutic responses for cancer patients." (PMID 40750759, 2025). "Given the elevated METTL5 expression in clinically “cold” tumors and poor responders, selective inhibition of METTL5 may provide a rational approach to overcome tumor immune evasion and broaden the efficacy of immunotherapy across otherwise refractory cancers." (PMID 41487998, 2025). "Additionally, METTL5's high expression in breast cancer and necessity for cancer cell growth, along with its homolog's role in Caenorhabditis elegans translation, underscore its critical function in cancer progression and translational regulation." (PMID 38797935, 2024). "Recent studies report that METTL5 could be related to cancer." (PMID 35166644, 2022). "METTL5 and TRMT112 are negatively related to other genes in some cancer types, especially in OV, PRAD, BRCA, and GBM." (PMID 39457524, 2024). "After that, TRMT112 is a small evolutionarily conserved protein and current studies revealed that METTL5 and its partner TRMT112 are upregulated in various cancers." (PMID 38453794, 2024). "It was likely to due to the METTL5 and METTL16 genetic variations function diversely on multiple cancers, and influence the progression of EOC through transcription modification." (PMID 38370381, 2024). "We surveyed commonly used cancer cell culture lines by Western blot and found that HeLa, HEL, and K562 cells showed relatively higher METTL5 expression." (PMID 35033535, 2022). "Given that the majority of patients in the pan‐cancer TCGA datasets have not received immunotherapy, our data suggest that upregulated METTL5 expression does not impact the prognosis of OC patients in the absence of immunotherapy." (PMID 41042068, 2025). "Although METTL5 expression does not correlate with overall survival and disease stages in cancer patients, HGSOC patients with upregulated METTL5 display unfavorable clinical outcomes in response to ICB treatment." (PMID 41042068, 2025). "Interestingly, METTL5 appears to regulate the same oncogenic target, such as MYC, across multiple cancer types." (PMID 41487998, 2025). "In addition to METTL5/TRMT112 complex, NSUN5 and snoRNAs, other key regulators also play significant roles in rRNA modifications and ribosome biogenesis, significantly influence cancer progression." (PMID 38797935, 2024). "Furthermore, METTL5 overexpression may induce NET release, influencing the tumor immune microenvironment and promoting distant cancer cell metastasis." (PMID 38613157, 2024).